TRIP6 (thyroid hormone receptor interactor 6)
Description:
Relays signals from the cell surface to the nucleus to weaken adherens junction and promote actin cytoskeleton reorganization and cell invasiveness. Involved in lysophosphatidic acid-induced cell adhesion and migration. Acts as a transcriptional coactivator for NF-kappa-B and JUN, and mediates the transrepression of these transcription factors induced by glucocorticoid receptor.
Synonyms: TRIP-6; OIP-1; ZRP-1; OIP1; MGC10556; MGC10558; MGC29959; MGC3837; MGC4423; TRIP6i2
Tractability: Antibody: its Gene Ontology location is reachable by antibodies, with high confidence.
Gene: Protein-coding gene on chromosome 7 (100,867,126 to 100,873,524, forward strand). Ensembl gene ENSG00000087077.
Subcellular location: Cytoplasm, cytoskeleton; Cell junction, focal adhesion; Nucleus; Cytoplasm
Subcellular location (Human Protein Atlas): Focal adhesion sites; Cytosol; Plasma membrane
Gene Ontology:
Molecular function: interleukin-1 receptor binding; kinase binding; protein binding; RNA binding; nuclear thyroid hormone receptor binding
Biological process: positive regulation of cell migration; positive regulation of non-canonical NF-kappaB signal transduction; focal adhesion assembly; signal transduction; chordate embryonic development
Cellular component: cytoplasm; cytoskeleton; cytosol; focal adhesion; nucleus; stress fiber
Genetic constraint (gnomAD): Loss-of-function variants: 33 observed, 48.97 expected, observed/expected ratio (o/e) 0.67, 90% interval 0.51 to 0.9. The upper end of that interval is the gene's LOEUF score, 0.9, which puts it in group 3 of 6, group 1 being the genes least tolerant of losing a copy. Missense variants: 661 observed, 636.54 expected, observed/expected ratio (o/e) 1.04, 90% interval 0.97 to 1.11. Synonymous variants: 255 observed, 264.98 expected, observed/expected ratio (o/e) 0.96, 90% interval 0.87 to 1.07.
Homologues: Orthologues: chimpanzee TRIP6 (99% identical), macaque TRIP6 (98% identical), pig TRIP6 (91% identical), guinea pig TRIP6 (90% identical), dog TRIP6 (89% identical), rat Trip6 (88% identical), mouse Trip6 (87% identical), zebrafish trip6 (54% identical), Caenorhabditis elegans unc-115 (16% identical). Paralogues in human: ZYX (38% identical).
Diseases named in the same sentence as TRIP6 in open-access papers:
TRIP6 is named in the same sentence as 38 diseases in open-access papers, as found by Europe PMC text mining. Sharing a sentence is not in itself a finding about the gene and the disease. The quoted sentences say what the papers report.
colorectal cancer (7 papers, 2022 to 2025). A primary or metastatic malignant neoplasm that affects the colon or rectum. "Additionally, aberrant expression of TRIP6 gene was associated with metastasis and drug resistance of colorectal cancer." (PMID 39882240, 2024). "This discovery not only provides a theoretical basis for TRIP6 as a potential therapeutic target in colorectal cancer, but also unveils its potential role as a key bridge linking intrinsic tumor cell characteristics with the external immune microenvironment." (PMID 41438741, 2025). "To date, a few studies have investigated the regulation of TRIP6 expression by microRNA (miRNA), in particular, miR-138-5p, miR-485-3p in neural stem cells, and miR-7 in colorectal cancer." (PMID 36833223, 2023). "Colorectal cancer cells are regulated by Trip6, a miR-7 target, through regulating proliferation and metastasis." (PMID 38054820, 2023). "Moreover, TRIP6 exhibits significant upregulation in colorectal cancer and correlates with various disease stages." (PMID 41311582, 2025). "Despite this, TRIP6's role in colorectal cancer (CRC), particularly its correlation with glucose metabolism and immune cell infiltration, remains unclear." (PMID 38369589, 2024). "TTPAL activates Wnt by stabilizing TRIP6/ β- Catenin signal promotes colorectal cancer." (PMID 38054820, 2023).
breast carcinoma (6 papers, 2012 to 2025). "Analysis of TRIP6 expression in 95 breast cancer samples revealed associations of the TRIP6 mRNA expression level with progesterone receptor positivity and premenopausal status." (PMID 36833223, 2023). "In conclusion, we demonstrated that TRIP6 is overexpressed in breast cancer cells and tissues and is associated with the poor prognosis of breast cancer patients." (PMID 32082081, 2020). "Luciferase reporter, subcellular fractionation and immunofluorescence staining assays were performed to determine the underlying mechanism of TRIP6-mediated stemness of breast cancer cells." (PMID 32082081, 2020). "Overexpression of TRIP6 is significantly associated with the relapse-free survival of breast cancer patients, and besides that, previous studies have shown that cancer stem cells (CSCs) play a key role in tumor recurrence, which suggests that TRIP6 may be involved in the regulation of stemness." (PMID 32082081, 2020). "In tumor biology, TRIP6 is widely recognized as an oncogene, exhibiting aberrantly high expression in various malignancies including breast cancer, gastric cancer, and ovarian cancer." (PMID 41438741, 2025). "Here, we exploited parental taxane-sensitive MCF-7 cells and two taxane-resistant sublines, MCF-7/PacR (named as “PacR” subline) and MCF-7/SB-T-0035R (named as “0035R” sublines), to elucidate mechanisms regulating TRIP6 expression in breast cancer." (PMID 36833223, 2023). "TRIP6 mRNA and protein level correlated intermediately (Spearman’s coefficient 0.594, p = 0.032) in breast cancer tissues." (PMID 36833223, 2023). "Ultimately, we found high TRIP6 mRNA levels in progesterone receptor-positive breast cancer and samples resected from premenopausal women." (PMID 36833223, 2023). "Nevertheless, BT549, MCF-7 and HCC70 cells expressed more TRIP6 mRNA than any other breast cancer cells in the study." (PMID 36833223, 2023). "For instance, thyroid receptor-interacting protein 6 (TRIP6) is an adapter protein that belongs to Lim proteins Zixin family and plays an important role in regulating the function of CSCs in breast cancer through regulation of Wnt/β-Catenin signaling." (PMID 35205716, 2022). "Recently, we reported alterations in ABCC3, CPS1, and TRIP6 gene expression in a breast cancer cell line resistant to paclitaxel." (PMID 35008510, 2021). "We have recently shown that the TRIP6 protein is significantly upregulated in breast cancer MCF-7 cells with acquired resistance to paclitaxel compared to the original sensitive MCF-7 cells." (PMID 35008510, 2021). "Regarding the third candidate molecule, it was reported that TRIP6, a zyxin family member being enriched at focal adhesions, has been markedly upregulated in paclitaxel-resistant breast cancer MCF-7/PacR cells." (PMID 35008510, 2021). "To determine the potential effect of TRIP6 in breast cancer, we first validated TRIP6 mRNA and protein expression level in six breast cell lines (MCF-10a, ZR-75-30, T47D, MDA-MB-231, MDA-MB-415, and BT549)." (PMID 32082081, 2020). "Taken together, our results showed that TRIP6 promotes the stem-like phenotype of breast cancer cells." (PMID 32082081, 2020). "Taken together, these data indicated that TRIP6 enhances proliferation, tumorigenesis and stemness of breast cancer cells, thus inducing the development and recurrence of breast cancer." (PMID 32082081, 2020). "MTT and colony formation assays indicated that the proliferation rate was significantly increased in TRIP6-transduced breast cancer cells compared with the vector cells, and conversely decreased in TRIP6-silenced breast cancer cells." (PMID 32082081, 2020). "Functional studies revealed that overexpression of TRIP6 significantly enhanced proliferative, tumorigenicity capability and the cancer stem cell-like properties of breast cancer in vitro and in vivo." (PMID 32082081, 2020). "Silencing β-catenin in TRIP6-tranduced cells strikingly reversed the spheroidizing ability of breast cancer cells." (PMID 32082081, 2020).
breast carcinoma (continued). "To explore the relationship between TRIP6 expression and the clinicopathological type of breast cancer patients, we detected the expression of TRIP6 protein in 340 paraffin-embedded breast cancer tissues." (PMID 32082081, 2020). "Herein, we reported that TRIP6 is overexpressed in breast cancer and enhances cell proliferation and tumorigenicity abilities and tumor-initiating abilities of cancer stem cells." (PMID 32082081, 2020). "Next, we conducted the mammosphere formation assay to detect the effect of TRIP6 on the self-renewal ability of breast cancer cells." (PMID 32082081, 2020). "To explore the mechanism of TRIP6-mediated stem-like characteristics in breast cancer, we next studied the relationship between TRIP6 expression and the genes regulated by various signaling signatures using GSEA of GEO datasets." (PMID 32082081, 2020). "Taken together, our results suggested that upregulation of TRIP6 promotes the proliferation, tumorigenicity and stemness of breast cancer cells through enhancing Wnt/β-catenin signaling." (PMID 32082081, 2020). "Collectively, our results provided strong evidence that TRIP6 plays a vital role in promoting cell proliferation and tumorigenicity of breast cancer cells." (PMID 32082081, 2020). "TRIP6 mRNA and protein expression were significantly elevated in five breast cancer cell lines compared to immortal human mammary epithelial cell line (MCF-10a)." (PMID 32082081, 2020). "TRIP6 expression in breast cancer cells and tissues were detected by Real-Time PCR, western blot and immunohistochemistry (IHC)." (PMID 32082081, 2020). "The results showed that with the increase of breast cancer clinical stage, the TRIP6 expression level was also upregulated in the tissues." (PMID 32082081, 2020). "In this study, the results of MTT, colony formation and tumorigenicity showed that TRIP6 promoted the proliferation and tumorigenesis of breast cancer cells in vitro and in vivo." (PMID 32082081, 2020). "Hence, we aimed to unveil the regulation of TRIP6 expression in MCF-7 breast cancer cells (with high TRIP6 expression) and taxane-resistant MCF-7 sublines (manifesting even higher TRIP6 expression)." (PMID 36833223, 2023). "To highlight our findings concerning the regulation of TRIP6 expression in sensitive and taxane-resistant MCF-7 breast cancer cell lines, we evaluated TRIP6 mRNA expression against clinical data of breast cancer patients who had undergone taxane-containing regimens." (PMID 36833223, 2023). "Therefore, TRIP6 is a potential novel prognostic biomarker and therapeutic target for recurrence of breast cancer." (PMID 32082081, 2020). "MTT assays, colony formation assays, Xenografted tumor model and mammosphere formation assays were performed to investigate the oncogenic functions of TRIP6 in the tumorigenic capability and the tumor-initiating cell-like phenotype of breast cancer cells in vitro and in vivo." (PMID 32082081, 2020). "In addition, mammosphere formation results indicated that TRIP6 overexpression enhanced the self-renewal ability of breast cancer stem cells, while silencing TRIP6 weakened the spheroidizing ability of breast cancer stem cells." (PMID 32082081, 2020). "Notably, we found that TRIP6 promoted Wnt/β-catenin signaling pathway in breast cancer to strengthen the tumor-initiating cell-like phenotype of breast cancer cells." (PMID 32082081, 2020). "In addition, breast cancer cells transduced with TRIP6 formed larger tumors and had higher tumor weights than vector control tumors." (PMID 32082081, 2020). "Notably, the results showed that TRIP6-transduced breast cancer cells formed larger and more spheres than vector cells, whereas TRIP6-silenced cells formed smaller and fewer spheres than shNT control cells." (PMID 32082081, 2020). "The present study aims to investigate the effects and mechanism of TRIP6 in breast cancer." (PMID 32082081, 2020).
breast carcinoma (continued). "Also, we found that TRIP6 is involved in activating Wnt/β-catenin pathway and promoting the expression of its downstream gene, resulting in enhanced proliferation ability of breast cancer cells and self-renewal ability of CSCs." (PMID 32082081, 2020). "In our study, we found that TRIP6 is upregulated in breast cancer cell lines and tissues." (PMID 32082081, 2020). "Statistical analysis further revealed that TRIP6 expression was significantly correlated with the clinical stage (P < 0.001), T classification (P = 0.019), M classification (P = 0.046) and relapse (P = 0.001) of breast cancer patients." (PMID 32082081, 2020). "This study indicates that TRIP6 plays an important role in maintaining the stem cell-like characteristics of breast cancer cells, supporting the significance of TRIP6 as a novel potential prognostic biomarker and therapeutic target for diagnosis and treatment of breast cancer." (PMID 32082081, 2020). "Finally, we evaluated the clinical data of breast cancer patients with TRIP6 mRNA expression." (PMID 36833223, 2023). "Furthermore, we assessed TRIP6 methylation in clinical breast cancer samples (TCGA study)." (PMID 36833223, 2023). "Because the results from the clinical specimens indicate that there is a correlation between TRIP6 expression and clinical stage and T classification, so we used stable TRIP6-transduced and TRIP6-silenced cells to further investigate the effect of TRIP6 on the proliferation of breast cancer cells." (PMID 32082081, 2020). "Furthermore, we studied whether TRIP6 could promote the tumorigenicity of breast cancer cells in vivo." (PMID 32082081, 2020). "Moreover, univariate and multivariate analyses indicated that TRIP6 expression was an independent prognostic factor for the breast cancer patients, which suggests that TRIP6 may represent a novel prognostic biomarker for breast cancer." (PMID 32082081, 2020). "Kaplan–Meier survival curves and the log-rank test showed that TRIP6 expression was significantly negatively correlated with the OS and RFS of breast cancer patients (P < 0.01)." (PMID 32082081, 2020). "Moreover, statistical analysis revealed that high TRIP6 expression is correlated with poor prognosis, short overall survival and relapse-free survival of breast cancer patients, indicating that TRIP6 may represent a potentially useful prognostic biomarker for breast cancer patients." (PMID 32082081, 2020). "High TRIP6 mRNA expression was observed in premenopausal (p = 0.033) and progesterone receptor positive (p = 0.020) breast cancer in the adjuvant cohort of breast cancer patients but not in the neoadjuvant cohort (p = 0.50 and p = 0.77, respectively)." (PMID 36833223, 2023). "Concerning miRNA, it was reported that miR-7, miR-138-5p, miR-485-3p, and miR-589-5p regulate TRIP6 gene expression; unfortunately, their function related to TRIP6 in breast cancer has not been investigated." (PMID 36833223, 2023). "TRIP6 expression was significantly upregulated in breast cancer, and was closely related to the clinicopathologic characteristics, poor overall survival (OS), relapse-free survival (RFS) and poor prognosis of breast cancer patients." (PMID 32082081, 2020). "Using partial and full length constructs of Cbl-c as bait in a yeast two-hybrid screen of breast cancer/prostate cancer, spleen, and brain cDNA libraries, the LIM domain containing proteins Hic-5 and Trip-6 were identified as potential Cbl-c interacting proteins." (PMID 23145173, 2012). "Moreover, the present study has not found direct prognostic or predictive relevance of TRIP6 for better tailoring breast cancer management at the clinics." (PMID 36833223, 2023). "Moreover, our results also confirmed that TRIP6 was overexpressed in six breast cancer tissues compared with corresponding adjacent noncancerous tissues." (PMID 32082081, 2020).
ovarian carcinoma (6 papers, 2013 to 2025). A malignant neoplasm originating from the surface ovarian epithelium. "LPAR2 has been linked to specific receptor-interacting proteins such as TRIP-6, through which it induces ovarian cancer cell migration." (PMID 23426604, 2013). "We estimated and observed changes in mRNA and protein profiles of ABCC3, CPS1, and TRIP6 in resistant and sensitive ovarian cancer cells and after the treatment of resistant ovarian cancer models with paclitaxel and Stony Brook taxanes in vitro and in vivo." (PMID 35008510, 2021). "In NCI/ADR-RES ovarian carcinoma cell line, we observed the highest level of TRIP6 mRNA followed by CPS1 and ABCC3 mRNA." (PMID 35008510, 2021). "In summary, our data show that TRIP6 cannot serve as a therapeutic target or prognostic biomarker in ovarian cancer at present." (PMID 35008510, 2021). "In conclusion, this study revealed the expression profile of three candidate molecules: ABCC3, CPS1, and TRIP6, previously associated with MDR phenomena, in resistant and sensitive ovarian carcinoma cell lines and EOC patients." (PMID 35008510, 2021). "We measured the mRNA expression level of ABCC3, CPS1, and TRIP6 in NCI/ADR-RES ovarian carcinoma cell line after 48 h cultivation with paclitaxel (3000 nM concentration), or novel generation taxanes SB-T-121605 and SB-T-121606 (300 nM concentration)." (PMID 35008510, 2021). "On the other hand, in ovarian cancer cells and glioblastoma cells that show persistent NF-κB activity and high levels of TRIP6, both A20 and CYLD bind to TRAF6 very weakly." (PMID 27134758, 2016). "Recently, we revealed no clinicopathological association of the TRIP6 mRNA expression level in ovarian cancer." (PMID 36833223, 2023). "Although the expression of the TRIP6 gene or protein was unchanged by taxane treatment of resistant ovarian cancer cell lines in vitro, the treatment of mice xenografts based on an NCI/ADR-RES model with experimental taxoid SB-T-121606 led to the TRIP6 protein downregulation in vivo." (PMID 35008510, 2021). "The next goal of this study was to assess whether ABCC3, CPS1, and TRIP6 might serve as biomarkers of prognosis, therapeutic response, and survival of ovarian carcinoma patients for improving therapy personalization." (PMID 35008510, 2021). "Indeed, under physiological conditions, TRIP6 bound to TRAF6 constitutively in SKOV-3 ovarian cancer cells that express TRIP6 and the LPA2 receptor at high levels." (PMID 27134758, 2016). "In contrast, depletion of TRIP6 by TRIP6-specific shRNA or Cas9/sgRNA greatly enhances the association of TRAF6 with A20 and CYLD, and attenuates lysophosphatidic acid-induced muclear factor-κB and JNK/p38 activation in ovarian cancer cells." (PMID 27134758, 2016). "Besides, TRIP6 could promote lysophosphatidic acid (LPA)-induced ovarian cancer cell migration by activating AKT signaling." (PMID 32082081, 2020). "In concordance with results observed in the in vitro model of paclitaxel-resistant ovarian carcinoma cell line NCI/ADR-RES, we observed the highest level to be that of TRIP6 mRNA, followed by ABCC3 and CPS1 transcripts in our set of EOC tumors." (PMID 35008510, 2021). "Taken together, these findings indicate a significant role for TRIP6 in LPA-stimulated NF-κB and JNK/p38 signaling in SKOV-3 ovarian cancer cells." (PMID 27134758, 2016). "The mRNA level of the TRIP6 gene was unchanged after the treatment with taxanes in the NCI/ADR-RES ovarian carcinoma cell line (data not shown)." (PMID 35008510, 2021). "Nevertheless, it is not known whether deregulation of ABCC3, CPS1 and TRIP6 occurs in different types of paclitaxel-resistant ovarian carcinoma cells or how the deregulation is affected by the action of paclitaxel and novel taxane derivatives." (PMID 35008510, 2021).
ovarian carcinoma (continued). "Nonetheless, depletion of TRIP6 by either shRNA or Cas9/sgRNA not only enhanced the association of TRAF6 with A20, but also with CYLD in untreated and treated cells, suggesting a significant role for TRIP6 in antagonizing the binding of TRAF6 to both A20 and CYLD in ovarian cancer cells." (PMID 27134758, 2016).